SLC2A12 (solute carrier family 2 member 12)
Description:
Insulin-independent facilitative glucose transporter.
Synonyms: GLUT12; GLUT8
Tractability: Antibody: its Gene Ontology location is reachable by antibodies, with high confidence; UniProt places it where antibodies can reach, with medium confidence; UniProt predicts a signal peptide or a membrane-spanning region. PROTAC: ubiquitination databases record sites on it.
Gene: Protein-coding gene on chromosome 6 (133,987,581 to 134,052,660, reverse strand). Ensembl gene ENSG00000146411.
Subcellular location: Cell membrane; Endomembrane system; Cytoplasm, perinuclear region
Subcellular location (Human Protein Atlas): Plasma membrane; Cell Junctions
Pathways (Reactome):
Transport of small molecules: Cellular hexose transport
Gene Ontology:
Molecular function: D-glucose transmembrane transporter activity; transmembrane transporter activity
Biological process: circulatory system development; hexose transmembrane transport; transmembrane transport
Cellular component: cell junction; plasma membrane; endomembrane system; membrane; perinuclear region of cytoplasm
Genetic constraint (gnomAD): Loss-of-function variants: 29 observed, 47.28 expected, observed/expected ratio (o/e) 0.61, 90% interval 0.46 to 0.84. The upper end of that interval is the gene's LOEUF score, 0.84, which puts it in group 3 of 6, group 1 being the genes least tolerant of losing a copy. Missense variants: 654 observed, 782.73 expected, observed/expected ratio (o/e) 0.84, 90% interval 0.78 to 0.89. Synonymous variants: 295 observed, 298.97 expected, observed/expected ratio (o/e) 0.99, 90% interval 0.9 to 1.09.
Homologues: Orthologues: chimpanzee SLC2A12 (99% identical), macaque SLC2A12 (98% identical), dog SLC2A12 (88% identical), pig SLC2A12 (88% identical), rabbit SLC2A12 (86% identical), mouse Slc2a12 (84% identical), rat Slc2a12 (83% identical), guinea pig SLC2A12 (83% identical), tropical clawed frog slc2a12 (58% identical), zebrafish slc2a12 (41% identical), Drosophila melanogaster nebu (21% identical), Drosophila melanogaster Tret1-2 (21% identical), and 40 more. Paralogues in human: SLC2A10 (35% identical), SLC2A13 (26% identical), SLC2A8 (23% identical), SLC2A2 (23% identical), SLC2A4 (23% identical), SLC2A1 (22% identical), SLC2A3 (22% identical), SLC2A14 (22% identical), SLC2A6 (20% identical), SLC2A7 (19% identical), SLC2A5 (19% identical), SLC2A9 (18% identical), and 1 more.
Diseases named in the same sentence as SLC2A12 in open-access papers:
SLC2A12 is named in the same sentence as 35 diseases in open-access papers, as found by Europe PMC text mining. Sharing a sentence is not in itself a finding about the gene and the disease. The quoted sentences say what the papers report.
breast carcinoma (12 papers, 2010 to 2025). "Moreover, higher mRNA expression of SLC2A5 and SLC2A12 significantly associated with worse prognosis of breast cancer patients (HR: 1.46 [1.18–1.82];p = 6E-04 and HR: 1.55 [1.12–2.14];p = 0.008, respectively)." (PMID 34488531, 2021). "In breast cancer cell lines, the insulin-sensitive glucose transporter 12 (SLC2A12) protein levels are increased with E2, suggesting a regulatory effect of estradiol on glucose metabolism." (PMID 38509416, 2024).
Hyperglycemia (4 papers, 2018 to 2025). An increased concentration of glucose in the blood. "As SLC2A12 is known to code for a glucose transporter, further studies on the role of the SLC2A12 and the correlation with metabolic regulations in TM can provide deeper insights into the relationship between hyperglycemia and POAG." (PMID 36176278, 2022). "For instance, this highlighted a 52 bp insertion in SLC2A12 (CADD-SV score: 51) found in a participant diagnosed with Type 2 diabetes and hyperglycemia." (PMID 41256123, 2025).
gout (2 papers, 2018 to 2022). A condition characterized by painful swelling of the joints, which is caused by deposition of urate crystals. "Another meta-analysis of GWASs on serum urea salt concentrations and gout in African Americans found genome-wide significance at three loci (SLC2A9, solute carrier family 2 member 12 (SLC2A12), and SLC22A12)." (PMID 35813212, 2022).
asthma (1 paper, 2021). "We identified SLC7A11, SLC2A12, ZEB1, ATF3, and HIC1 common between DEGs and TFs involved with asthma and ferroptosis." (PMID 34257337, 2021).
breast tumors (1 paper, 2023). "Specifically, SLC2A1, SLC2A6, SLC2A10, and SLC2A13 were significantly overexpressed, whereas SLC2A3, SLC2A4, SLC2A9, SLC2A11, and SLC2A12 had downregulated expressions in breast tumors compared with those in normal breast epithelium." (PMID 37108300, 2023).
COVID-19 (1 paper, 2025). A disease caused by infection with severe acute respiratory syndrome coronavirus 2. "The hypermethylated genes with lowest p-values for hospitalized COVID-19 patients at inclusion (T1) and at 6 weeks post-inclusion (T2) versus HCs included NXN, SLC2A12, RAD54L2, GIMAP5, and PPP2R5C, while the top five hypomethylated genes with lowest p-value were, LOC101928650, DLX5." (PMID 41227320, 2025).
diabetes (1 paper, 2019). "Increased active SLC2a-12 content was observed at the surface of diabetic cardiomyocytes as a compensation of GLUT-4 downregulation during diabetes." (PMID 30823517, 2019). "Out of these 15 predicted genes, we selected 4 target genes (IGF-1, SLC2a-12, EIF-4e, and ULK-2) based on the available literature related to myocardial function and/or diabetes for experimental validation." (PMID 30823517, 2019).
intracranial aneurysms (1 paper, 2022). "Although the roles of GLUTs in the pathogenesis of intracranial aneurysms have not been elucidated clearly, we hypothesize that SLC2A12 is related to IA formation." (PMID 35918429, 2022).
lung carcinoma (1 paper, 2022). "H1299 (NSCLC cell line) has high SLC2A12 mRNA expression, while lung cancer cell line A549 has high levels of GLUT-12 expression." (PMID 36518662, 2022).
ovarian carcinoma (1 paper, 2025). A malignant neoplasm originating from the surface ovarian epithelium. "In ovarian cancer models, hypoxia induces HIF-1α to upregulate solute carrier family 2 member 12 (SLC2A12), engaging glutathione metabolism, inhibiting ferroptosis, and promoting tumor progression and drug resistance." (PMID 41462613, 2025).
Sensory neuropathy (1 paper, 2019). Peripheral neuropathy affecting the sensory nerves. "We found that SLC2a-12 (or GLUT-12) was regulated by miR-98, let-7a, and miR-466b, and its myocardial mRNA level increased after systemic-capsaicin-treatment-induced sensory neuropathy." (PMID 30823517, 2019). "This is the first demonstration that sensory neuropathy affects cardiac miRNA expression network targeting IGF-1, SLC2a-12, EIF-4e, and ULK-2, which may contribute to cardiac diastolic dysfunction induced by sensory neuropathy." (PMID 30823517, 2019). "This is the first demonstration that sensory neuropathy induced by capsaicin desensitization affects cardiac miRNA expression network targeting IGF-1, SLC2a-12, EIF-4e, and ULK-2, which may contribute to cardiac diastolic dysfunction induced by sensory neuropathy." (PMID 30823517, 2019).
tumor (15 papers, 2010 to 2025). "Another study indicated that the diagnostic value of exosomal lncRNA SLC2A12-10:1 in discriminating GC patients from healthy subjects was higher than traditional tumor biomarkers, which highlighted the potential utility of this exosomal lncRNAs as novel tumor markers for GC screening." (PMID 33430032, 2021). "Additionally, lower levels of SLC2A3, SLC2A6, SLC2A9, SLC2A12, and SLC2A14 and higher levels of SLC2A1, SLC2A5, SLC2A10, and SLC2A11 had an association with advanced tumor stage." (PMID 36518662, 2022). "A lower differentiation grade tumor is implied by overexpression of SLC2A1, SLC2A5, SLC2A10, SLC2A11and lower levels of SLC2A3, SLC2A6, SLC2A9, SLC2A12, and SLC2A14, emphasizing the possibility of these molecular roles for predicting the course of the tumor." (PMID 36518662, 2022). "LUAD tumor tissues showed higher mRNA expressions of SLC2A1, SLC2A5, and SLC2A12 and lower expressions of SLC2A3, SLC2A4, SLC2A6, SLC2A9, and SLC2A14." (PMID 36518662, 2022). "Among those, SLC2A12, TXNIP, and MAFG were found to have low expressions in the tumor tissue samples, while the others were highly expressed." (PMID 34386423, 2021). "Furthermore, SLC2A3, SLC2A6, SLC2A9, SLC2A12, and SLC2A14 levels were lower in patients with advanced tumor stages, suggesting that these genes might act as a barrier to the progression of LUAD." (PMID 36518662, 2022).
cancer (14 papers, 2011 to 2026). A tumor composed of atypical neoplastic, often pleomorphic cells that invade other tissues. "Although SLC2A12 has been associated with certain types of cancer, specific details regarding its exact function, biochemical properties, and significance in human physiology are not as well-documented as other members of the SLC2 family." (PMID 39057031, 2024). "The high or specific expression of other glucose transporters such as GLUT2/SLC2A2, GLUT3/SLC2A3, GLUT12/SLC2A12 and the fructose transporter GLUT5/SLC2A5 has also been associated with various cancer types and specific cancer stages." (PMID 36770817, 2023). "The glucose transporter member SLC2A12, alias GLUT12, has been recognized as a major glucose transporter in cancer and therefore considered as a possible therapeutic cancer target." (PMID 27096627, 2016).
SLC2A12 also shares sentences with these, for which no sentence is quoted: prostate carcinoma (7 papers); triple-negative breast carcinoma (4); heart failure (3); Alzheimer disease (2); gastric cancer (2); hepatocellular carcinoma (2); prostate tumors (2); schizophrenia (2); Ataxia (1); bladder cancer (1); dilated cardiomyopathy (1); foetal macrosomia (1); gestational diabetes (1); glaucoma (1); Insulin resistance (1); myocardial infarction (1); neuroblastoma (1); neuropathy (1); Obesity (1); placental insufficiency (1); type 1 diabetes (1); Type 2 diabetes (1).